MSH6 (mutS homolog 6)
Diseases named in the same sentence as MSH6 in open-access papers (continued):
Sharing a sentence is not in itself a finding about the gene and the disease.
tumor (continued). "In fact, no instability was found among any of the five repeat loci in the MSI tumor with isolated MSH6 loss in our study." (PMID 32108923, 2020). "Tumor sequencing identified two MSH6 nonsense variants, a hotspot POLE mutation and a mutational signature supportive of a germline MMR deficiency with a somatic POLE mutation." (PMID 31604779, 2019). "A fifth patient (PD31196a) was found to have a pathogenic germline mutation in MSH6 (p.V878A) with somatic loss of the wild-type allele in the tumor." (PMID 30889380, 2019). "Tumour sample from the carrier of this variant had loss of MSH6 protein expression, further supporting its pathogenicity." (PMID 30324682, 2018). "Loss of function of MSH6 (or of other MMR proteins) has been shown to confer profound resistance to TMZ in a variety of tumor cell lines." (PMID 30274152, 2018). "Altogether, these results present loss of MSH6 expression as a protective backup mechanism of tumor cells under conditions of inactivated MGMT." (PMID 30274152, 2018). "In three cases with the MSH6 p.Leu585Pro germline mutation, the stains were weak but present in >1% of cells and a second tumour mutation was found on ColoSeq indicating that these tumours developed as a result of LS." (PMID 28466842, 2017). "Sporadic tumour development is likely more common with the lower penetrance mutations in MSH6 and PMS2." (PMID 28466842, 2017). "This tumor also harbored a somatic, predicted deleterious missense mutation located on the MutS domain II of MSH6 (C687Y)." (PMID 28153049, 2017). "CpG probes at MSH6 showed consistently higher levels of methylation within the tumor-derived DNA across six probes, two of which were associated with its promoter (Δβ 4.09%; adj." (PMID 27902704, 2016). "For example, mice homozygously-deficient in Msh6 show a strong tumor phenotype, but there is little increase in heterozygous mice." (PMID 25742645, 2015). "Only 7.1% (3 out of 42) of patients with a MSI / EMAST tumor showed loss of expression of the MSH6 protein, compared to 62.5% (5 out of 8) of patients with MSI / non-EMAST tumors." (PMID 25884216, 2015). "In contrast, germline mutations in MSH6 or PMS2 cause isolated loss of the encoded protein in the tumor tissue." (PMID 22547953, 2011). "Our study was restricted to tumour samples that showed a deficiency in MSH6 expression only, as identified by IHC." (PMID 21081928, 2010). "The total size of the five PCR products obtained using the original pentaplex assay or commercial kit was calculated for each MSH6-deficient tumour in order to compare it with the TVR observed in normal DNA." (PMID 21081928, 2010).
tumor (continued). "The MSH6 protein is not involved in the repair of mismatches of two nucleotides in length and consequently the three dinucleotide repeats of the NCI panel often show stability in MSH6-deficient tumours." (PMID 21081928, 2010). "These eight MSH6-deficient tumours showed instability at five markers (three cases), four markers (four cases) and three markers (one case)." (PMID 21081928, 2010). "The present study represents the first systematic analysis of a large series of MSH6-deficient tumours using the five mononucleotide repeats that comprise the pentaplex assay." (PMID 21081928, 2010). "There is clearly a need for further work to identify markers that are specific for MSH6-deficient tumours." (PMID 21081928, 2010). "In the present study, 29 tumour samples with MSH6 deficiency were collected from three Dutch and one French cancer centres and evaluated for MSI status using the pentaplex panel." (PMID 21081928, 2010). "There is no routine screening for MSH6 in our laboratory and it is only performed when there is loss of MSH6 expression in the tumour (IHC) or a family history indicating MSH6 mutation." (PMID 20487569, 2010). "Like in previous studies our study shows that mononucleotide markers but not dinucleotide markers are sensitive to show instability in tumours of MSH6 mutation carriers." (PMID 17117178, 2006). "In none of the 76 patients with CRC, or in the 13 patients with other HNPCC-related tumours a pathogenic germline mutation in MSH6 was detected." (PMID 17117178, 2006). "In our study, the patients with MSI-stable/low tumours that were analysed for MSH6 mutations were mainly diagnosed before the age of 50." (PMID 17117178, 2006). "Similarly there is evidence that MSH6 deficient tumours have lower MSI or are actually microsatellite stable." (PMID 40651337, 2025). "Concordant with the lack of MSH6 protein in immunohistochemical stainings, DNA extracted from the paraffin embedded tumor lesion carried a mutation in MSH6 (p.X1267_splice), classified as pathogenic and likely pathogenic in the InSiGHT and ClinVar Databases, respectively." (PMID 41120797, 2025). "All four patients were found to have a germ line mutation for MSH6, but their tumours were MSS." (PMID 40133691, 2025). "A mutation in MutS homolog 6 was found solely in the tumor tissue." (PMID 40696621, 2025). "Age, tumor size and MSH6 mutations only show a trend towards significance (p-value < 0.1)." (PMID 39286015, 2024). "These plots show a WT reference allele (0 peak, in beige), representing WT tumor alleles plus stromal admixture, and several contracted or expanded tumor alleles depending on MSH6/MSH3 homopolymer mutation within a sample on either side of the reference allele count (workflow)." (PMID 38956208, 2024). "However, we find that tumours with defects in a gene called MSH6, especially when associated with LS, are only detected efficiently with immunohistochemistry." (PMID 39682157, 2024).
tumor (continued). "Tumor stage and MSH6 mutation status were found to be significant predictors of PFS (p < 0.05)." (PMID 38746969, 2024). "Further studies are needed to determine whether loss of MSH6 in some tumor cells is mechanistically related to the expression of variant MSH3 or not." (PMID 38243056, 2024). "Associated sporadic nuclear loss of MSH6 protein was also observed in some tumor cells." (PMID 38243056, 2024). "In here, we found four tumors that were MSI-H but with retained MMR-proteins with either of the two types of assays but only one of these cases could be explained by a germline MSH6 missense variant, in which 30% of the tumor cells expressed all MMR proteins." (PMID 37143941, 2023). "Both were MSH6 frameshift mutations (p.A61fs and p.Y397fs), one of which was confirmed to be somatic and the other had uncertain somatic versus germline origin due to tumor-only sequencing analysis." (PMID 38079020, 2023). "The tumor also present MMR deficiency with MSH6 loss inconsistent with the MSS status which may be a secondary event induced by the novel pathogenic POLE T278K mutation." (PMID 36765365, 2023). "MMR immunohistochemical staining of the tumor showed solitary loss of MSH6 protein expression." (PMID 37318702, 2023). "The loss of MSH6 expression in the tumor could be interpreted by the two nonsense mutations (p.E1234* and p.E1322*) of the MSH6 gene which may lead to truncated proteins." (PMID 36765365, 2023). "Genetic analyses identified an MSH6 germline mutation and a high tumor mutation burden (TMB)." (PMID 36582237, 2022). "However, only one (25%) of the four neoplasms with isolated MSH6 loss had concurrent MSI-High results." (PMID 36230473, 2022). "Our mutational analysis revealed MSH6 mutation in tumor T‐10." (PMID 34351088, 2022). "Only a single EMAST‐negative and MSS tumour showed isolated loss of MSH6." (PMID 35099128, 2022). "However, it was reported mutated at a comparatively high rate (8.7%) in the present study, mainly due to mutations of MSH6 detected in two tumor samples." (PMID 35359413, 2022). "However, when preneoplasia and first cancer were pooled, the risk for onset of pre/neoplasia was significantly increased among carriers of MSH6 c.3936_4001+8dup (intronic) alone, (p = 0.034)." (PMID 36612224, 2022). "This patient carried a germline mutation in MSH6 (T29), which was also present in non-tumor tissue." (PMID 33435234, 2021). "It is well known that suppression of MSH6 is associated with a variety of tumours." (PMID 34440667, 2021). "Case 45 was an UCEC sample with 30% tumor cells and isolated loss of MSH6 by IHC." (PMID 34145315, 2021). "A causative role for MSH6 in cancer development was excluded based on tumor characteristics." (PMID 33811277, 2021).
tumor (continued). "Indeed, the indel spectrum of the only case presenting a MSS tumor (and isolated loss of MSH6 by IHC), LLS06, is exclusively composed by IDA-linked alterations." (PMID 33809179, 2021). "Herein, we report a patient with CMMRD and metastatic CRC resulting from bi-allelic germline MSH6 mutation who had heterogeneous MMR-IHC with high tumor mutations burden (TMB-H) but microsatellite stable (MSS) status that led to his complicated response to immune checkpoint inhibitor (ICI) therapy." (PMID 33422121, 2021). "However, immunohistochemistry analysis performed in the tumor of the proband showed loss of expression for MSH6, suggesting that this variant has a deleterious effect on the protein." (PMID 33008098, 2020). "The highest mutational burden was found in a tumor with a pathogenic mutation in MSH6 (F50_167)." (PMID 33227964, 2020). "Furthermore, studies showed that tumors with MSH6 deficiency, or certain tumor types such as endometrial cancer, were difficult to assess by the dinucleotide repeat markers." (PMID 31983041, 2020). "Investigating MMR gene mutations and methylation status in MSI tumor samples, we only observed few cases of MSH6 (MutSα), MSH3 (MutSβ), PMS2 (MutLα), PMS1 (MutLβ), and MLH3 (MutLγ) high-impact mutations often in combination with inactivation of other MMR genes." (PMID 29636374, 2018). "Moreover, three cases with complete loss of MLH1 and PMS2 expression in all three tumour blocks also displayed subclonal loss of MSH6 expression (10%, 20% and 90% of the tumour respectively) in one tumour block." (PMID 28424422, 2017). "We identified two individual's tumours with hypermutator phenotypes (HKNPC-003, HKNPC-033) with 2,051 and 817 somatic mutations in coding regions, respectively; both tumours harboured mutations of mismatch repair genes, including MSH6 (HKNPC-003) and MLH1 (HKNPC-033)." (PMID 28098136, 2017). "Private mutations in DNA mismatch proteins like MSH6 most likely lead to a significant gain of mutational burden in circumscribed regions of the tumor and thereby might have crucial impact on clinical management." (PMID 28146430, 2017). "In keeping with this, tumor formation rarely arises as a consequence of loss of only Msh6 or Msh3." (PMID 23821616, 2013). "However, tumours from patients with a pathogenic germline mutation in MSH6 can sometimes present an MSI-L phenotype with the NCI panel." (PMID 21081928, 2010). "Consequently, tumours with MSH6 deficiency are generally stable at dinucleotide repeats, and their MSI status is therefore debatable." (PMID 21081928, 2010). "MSH6-deficient cells are unable to repair single base mismatches, whereas they retain proficiency to repair two, three and four base loops, thus, causing only mononucleotide repeat instability in tumours." (PMID 20160730, 2010).
tumor (continued). "Several studies have confirmed the sensitivity, specificity and ease of use of the pentaplex panel; however, its sensitivity for the detection of MSH6-deficient tumours is so far unknown." (PMID 21081928, 2010). "Preliminary data had suggested that MSH6-deficient tumours could be detected using mononucleotide repeats, but these studies were performed with a limited number of markers and tumours." (PMID 21081928, 2010). "Similarly, in this report, we presented a case of EC whose tumor was ultra-mutated and dMMR with MSH6 loss may be driven by the somatic POLE T278K mutation and the secondary somatic MSH6 mutations (E1234* and E1322*)." (PMID 36765365, 2023). "This near genomic haploidization may likely have served as the tumor-initiating event by eliminating the remaining MSH6 wildtype allele, thereby resulting in the mismatch repair deficiency that led to accumulation of mutations in oncogenes and tumor suppressor genes that drove tumor development." (PMID 38079020, 2023). "Interestingly, recent data concerning biomolecular characteristics of GS documented that, although GS has a genetic profile that overlaps with GBM and other neoplasms, it is also true that GS has its genetic mutations, such as MSH6, BRAF, SUZ12, SOX2, and FBXW7." (PMID 38202090, 2023). "Somatic MSH6 mutations result in resistance to temozolomide and may accelerate tumor progression." (PMID 35370679, 2022). "Furthermore, the tumor of this patient showed a complete loss of MSH6 staining." (PMID 33467460, 2021). "However, it is well known that tumours caused by MSH6 mutations may show lower levels of MSI and may be classified as MSS or MSI-low." (PMID 24790682, 2014). "However, the efficiency of the pentaplex panel for the detection of MMR-deficient tumours with an MSH6 mutation is currently unknown and is the subject of the present investigation." (PMID 21081928, 2010). "It has been observed before that deleterious MSH6 mutations may be accompanied by MSI-low tumours." (PMID 12373605, 2002).